IL17A (interleukin 17A)
Diseases named in the same sentence as IL17A in open-access papers (continued):
Sharing a sentence is not in itself a finding about the gene and the disease.
asthma (continued). "There is growing evidence that IL-17A contributes to the development of asthma, particularly severe asthma characterized by intense neutrophil infiltration of the airways." (PMID 38579176, 2024). "IL-17A and IL-17F have the potential to control the influx of neutrophils in conditions such as asthma, lung allograft rejection, and cystic fibrosis." (PMID 38216608, 2024). "On the other hand, shikonin alleviated the imbalance of Th1/Th2 and Th17/Treg by regulating IFN-γ/FOXP3 and IL-4/IL-17A in asthma mice." (PMID 39444792, 2024). "The expression of IL-17a is increased in the BALF of patients with moderate-to-severe asthma, and the expression of the mucin gene is increased in human airway epithelial cells." (PMID 39349422, 2024). "IL-17A, in particular, enhances smooth muscle contraction and airway remodeling, contributing to asthma’s hyperreactive nature." (PMID 39594870, 2024). "In animal studies focused on asthma, it has been discovered that Th17 cells and related cytokines (such as IL-17A) are involved in recruiting inflammatory cells to the airways, especially in cases where asthma is severe." (PMID 39539452, 2024). "The study found that this combination significantly reduced the presence of Th2/Th17-derived cytokines (IL-4, IL-5, IL-13, IL-17A), immunoglobulin E, and leukotriene C4 in bronchoalveolar lavage fluid and serum, key contributors to allergies and asthma." (PMID 39857357, 2024). "This means that serum levels of total IgE were increased by increasing the severity of asthma, while the serum levels of IL-17A were decreased." (PMID 38660682, 2024). "The children with asthma had an inflammatory profile that was characterized by increased levels of several pro-inflammatory cytokines, including IL-2, IL-5, IL-13, IL-17A, IL-22, IL-33, TNF-α, and reduced level of anti-inflammatory cytokine, IL-10." (PMID 39902293, 2024). "Increased expression of IL-17A and IL-17F mRNA and protein has been observed in individuals with obesity-related asthma, suggesting a unique asthma phenotype." (PMID 39539452, 2024). "In contrast, other studies have demonstrated that severe asthma episodes are associated with high IFN-γ and IL-17A expression in the airways." (PMID 39439788, 2024). "Recent studies have demonstrated the involvement of Th17 lymphocytes in the pathogenesis of asthma mediated by IL-17A and TNF-α." (PMID 39598135, 2024). "IL-17A drives inflammation and oxidative stress, affecting the progression of chronic lung diseases (asthma, chronic obstructive pulmonary disease (COPD), lung cancer, and cystic fibrosis)." (PMID 38999871, 2024). "In individuals with moderate to severe asthma, an upregulation of IL‐17A levels was observed in Th17 cells, as well as in the plasma and culture supernatant." (PMID 38888451, 2024). "It has also been reported that in severe and treatment-resistant asthma, Th17 cell activation leads to the release of inflammatory mediators IL-17A and IL-17F." (PMID 39539452, 2024). "On a model of obesity and asthma, celastrol therapy reduced the frequency of Th17 cell growth and IL-17A production in the lung and serum." (PMID 37251328, 2023). "Numerous genetic variations linked to obesity-related asthma have been pinpointed in research studies, encompassing ADIPOQ, retinoid-related orphan receptor C (RORC), IL17A, TNF-α, beta-2 adrenergic receptor (ADRB2), and IL-6." (PMID 37834850, 2023). "In a very small study of 23 patients with steroid resistant asthma, IL-17A and IFN-γ were elevated in comparison to patients with steroid sensitive asthma." (PMID 40980110, 2023). "It is important in several diseases, including chronic obstructive pulmonary disease, cystic fibrosis, and asthma, and clinical trials have been planned to target IL-17A as a treatment for patients with inadequately controlled or steroid-resistant asthma." (PMID 36793128, 2023).
asthma (continued). "In vitro studies using stimulated neutrophils from children with asthma exacerbation have shown that it can induce the formation of IL-17A-enriched NETs." (PMID 38283037, 2023). "This study unveils the inflammatory effect of IL-17A-enriched asthma NETs on human lung fibroblasts, possibly correlating them with the fibrotic events of the disease." (PMID 37626601, 2023). "Sputum neutrophilia in asthma is strongly associated with increased production of several cytokines including IL-1β, IL-6, CXCL8, IL-12, IL-17A and TNF, and this correlates with bacterial burden, in particular Gamma-proteobacteria." (PMID 37180449, 2023). "Deletion or inhibition of SIRT6 results in impaired IL-17A secretion in airway epithelium and ameliorates airway remodeling in severe asthma via RORγt-K192 deacetylation." (PMID 38135684, 2023). "Recent studies show the presence of type 1 and 17 inflammation, characterized by increased neutrophils and IL-17A and IFNγ levels, are more common in older individuals with asthma." (PMID 37047327, 2023). "Here we identify epithelial sirtuin 6 (SIRT6) as an epigenetic regulator that governs IL-17A pathogenicity in severe asthma." (PMID 38135684, 2023). "Collectively, these results indicated that elevated epithelial SIRT6 promoted IL-17A release, which induced MMPs and cytokines (eg, Mmp3, Mmp12, and Cxcl1) scretion in severe asthma." (PMID 38135684, 2023). "Morever, we assessed the efficacy of SIRT6-targeted therapy with a inhibitor OSS had effects on the restoration of airway remodeling via inhibiting IL-17A-mediated mesenchymal reprogramming and airway inflammation in acute and chronic experimental asthma." (PMID 38135684, 2023). "The ability of 1,8-cineole to reduce IL-17A expression was previously demonstrated in a mouse model of asthma." (PMID 37047133, 2023). "Interleukin-17A (IL-17A), a proinflammatory cytokine that exacerbates allergic airway responses, is produced more frequently during viral asthma exacerbations." (PMID 37588324, 2023). "Several studies have associated IL-17A with airway remodeling and AHR, the major physiological characteristics of asthma." (PMID 37377958, 2023). "It has also been found that IL-17A and IL-17F exert different biological effects on the airway inflammation of asthma." (PMID 37377958, 2023). "It was reported that IL-17A induced Th17 cells to recruit neutrophils in the airway of steroid-resistant asthma and Th17 cells played an important part in steroid-resistant asthma with neutrophilic airway inflammation." (PMID 37208441, 2023). "In our study, wild-type mice were treated with recombinant IL-17A (i.n.)three times in an OVA asthma model to follow the influence of IL-17A on the development and progression of allergic asthma." (PMID 37443808, 2023). "Experiments in an animal asthma model have shown that blocking IL-17A or its receptor can reduce neutrophilic inflammation." (PMID 37626601, 2023). "The microenvironment of asthma triggers the release of NET-bound IL-17A with a pro-fibrotic activity." (PMID 37626601, 2023). "In our study, lncRNA CRNDE inhibited EMTs in lung epithelial cells via the downregulation of the miR-29a-3p/MCL-1 axis, which resulted in Th17/IL-17A effects that reduced asthma signs." (PMID 36743692, 2023). "The lncRNA CRNDE inhibited EMT in lung epithelial cells via the miR-29a-3p/MCL-1 axis and affected Th17/IL-17A to reduce asthma signs." (PMID 36743692, 2023). "In children with exacerbation of asthma, there is a significant increase in IL-17A levels in their sera." (PMID 38283037, 2023). "In asthma patients, the Th1- and Th17-mediated inflammation characterized by infiltration of Th cells producing interferon (IFN)-γ and IL-17A and neutrophil infiltration is associated with more severe disease and reduced CS sensitivity." (PMID 38203630, 2023).
asthma (continued). "The AA genotype of IL17A rs2275913, the TT genotype of IFNG rs2069705 and allelic A variants of TNFA rs1800629 are associated with mild asthma, and the TT genotype of IFNG rs2069705 is additionally associated with controlled asthma." (PMID 37465198, 2023). "Smoking is another strong environmental trigger of macrophage activation and production of IL-17A, IL-6 and IL-8, leading to airway neutrophilia in asthma patients." (PMID 37189844, 2023). "NETs, neutrophilic proteins (e.g., neutrophil elastase) and NET-specific immunoproteins (e.g., IL-17A) hold promise as biomarkers of asthma and for the development of more effective therapies in the future." (PMID 37626601, 2023). "Patients with severe asthma have higher levels of IL-17A in their airways when their diseases are more severe." (PMID 37920459, 2023). "In this study, we investigated the interaction of IL-17A with an allergic TH2 response in a mouse model of asthma." (PMID 37443808, 2023). "IL-17A secreted by Th17 cells was detected in samples of bronchial epithelial tissue from patients with more severe symptoms of asthma." (PMID 37445595, 2023). "Brodalumab, A new molecule, the anti-IL-17 receptor A monoclonal antibody can block IL-17A and IL-25 signaling, effective only in asthmatic patients with high IL-17, consistent with late-onset obesity-related asthma." (PMID 38292857, 2023). "Th17 cells and IL-17A are increased in the asthmatic airway, particularly in individuals with neutrophilic or more severe asthma." (PMID 37163370, 2023). "It has been previously shown that AHR in murine asthma models is increased by additional stimulation with IL-17A." (PMID 37443808, 2023). "Asthma endotypes with increased type 1 or 17 inflammation have increased neutrophil infiltration and are mediated by effector cytokines, namely IFNγ and IL-17A, respectively." (PMID 37047327, 2023). "Experimental mouse models of asthma suggest that IL-17A enhances the recruitment of bronchial neutrophils through CXCR2 signaling." (PMID 37377958, 2023). "The in vitro stimulation of control neutrophils using the sera from pediatric patients during asthma exacerbation resulted in IL-17A-enriched NET formation." (PMID 37626601, 2023). "These cells can concomitantly produce IL-17A and type 2 cytokines, and have induced more severe asthma than classical Th2 and Th17 cells." (PMID 36793128, 2023). "Herein, we identify neutrophils/NETs expressing IL-17A as a main component of asthma exacerbation (hereafter mentioned as asthma) in children." (PMID 37626601, 2023). "In whole lung tissue, it was upregulated in the IL-17A + OVA asthma group compared to all other groups." (PMID 37443808, 2023). "To evaluate the role of IL-17A in allergic inflammation and asthma, we chose a mouse model using the chicken ovalbumin as the model allergen." (PMID 37443808, 2023). "For example, cyanidin was reported to attenuate IL-17A–induced skin hyperplasia, alleviate airway hyperreactivity, and inhibit inflammation induced by IL-17–producing TH17 cells in severe asthma and steroid-resistant model." (PMID 36830086, 2023). "In contrast, downregulation of lncRNA CRNDE in the lung epithelial cells of mice reduced asthma signs via Th17/IL-17A effects." (PMID 36743692, 2023). "Several studies showed that obese patients with asthma presented a sputum inflammatory pattern characterized by increased IL-17A expression and a higher percentage of neutrophils in sputum than non-obese asthmatic patients." (PMID 37189844, 2023). "Increased levels of NETs and interleukin (IL)-17A were detected in the sera of children during asthma exacerbation." (PMID 37626601, 2023). "Collectively, these results uncover a function for SIRT6 in regulating IL-17A pathogenicity in severe asthma, implicating SIRT6 as a potential therapeutic target for severe asthma." (PMID 38135684, 2023).
asthma (continued). "IL-17A is now considered an important player in the pathogenesis of human respiratory diseases such as asthma, chronic obstructive pulmonary, and cystic fibrosis." (PMID 37238999, 2023). "Human anti-IL-17A antibodies (secukinumab and ixekizumab) are currently approved to treat inflammatory diseases other than asthma, such as plaque psoriasis." (PMID 35454142, 2022). "IL-17A was shown to be upregulated in airway biopsy specimens and sputa from patients with moderate-to-severe asthma." (PMID 35454142, 2022). "IL-17A regulates several airway epithelial functions in asthma and COPD, including stimulation of immune responses, airway remodeling, and mucus production." (PMID 35773318, 2022). "During asthma exacerbations the cytokines IL-8 and IL-17A prolong the life span of the neutrophil and modulates Th2 and innate immune responses." (PMID 36362795, 2022). "The frequent consumption of products such as vegetables, fruit, eggs, groats (e.g., buckwheat, barley, millet) lowered the concentration of IL-17A in a study on about 700 children with asthma." (PMID 35277002, 2022). "In contrast, other asthma models mimicking more neutrophilic or severe asthma endotypes clearly demonstrated a pathological role for the IL-17A/IL-17F/IL-17RC axis in the modeled diseases." (PMID 35883573, 2022). "In patients with mild asthma, combustible cigarette smoking increases neutrophil counts, and IL-17A, IL-6, and IL-8 levels." (PMID 35626330, 2022). "Meanwhile, the RNA levels of IL-17A and RORγt in the asthma patients were significantly higher than those in the normal controls." (PMID 35528611, 2022). "A previous study demonstrated that mucosa airway biopsies of patients with severe asthma have increased expression of both IL-17A and IL-17F." (PMID 36517803, 2022). "Peripheral blood mononuclear cells from patients with severe asthma reportedly exhibit an enhanced capacity to synthesize IL-17A and IL-22 following in vitro activation." (PMID 35454142, 2022). "Taken together, our findings showed that RV infection induced aberrant host immune responses mediated by IFN-γ, IL-17A, and IL-6 in asthma." (PMID 36366542, 2022). "IL23 promotes the development of Th17 lymphocytes, and these cells elaborate IL17A, which is important for the recruitment of neutrophils to the airways in non-T2 asthma." (PMID 36237537, 2022). "In contrast, during asthma exacerbation, another work has found increased levels of IL-17A from nasal lining fluid and increased frequency of Th17 cells in peripheral blood of asthmatic patients." (PMID 36032162, 2022). "Taken together, these findings indicate that IL-17E acts differently to its relatives IL-17A and IL-17F in asthma pathogenesis." (PMID 35883573, 2022). "In recent years, many studies have shown that Th17 cells and Th17 secreted cytokines such as IL-17A are involved in inflammation in asthma and promote the development of asthma." (PMID 35355985, 2022). "By increasing glucocorticoid insensitivity, smooth muscle hypercontractility, and neutrophil migration to the airways, IL-17A has been shown to contribute to the pathophysiology of asthma." (PMID 35664352, 2022). "An asthma cell model was established with interleukins (IL-4, IL-13 and IL-17A) and transfected with siRNA-CXCR1." (PMID 36575422, 2022). "The levels of IL-17A in sputum, nasal and bronchial biopsies and serum have been reported to be higher in asthma and COPD patients than healthy controls." (PMID 35773318, 2022). "Many studies have confirmed that IL‐17A is involved in the development of severe asthma, which is characterized by neutrophil infiltration in the airway." (PMID 35344278, 2022). "Combined neutralization of both IL-13 and IL-17A diminished the pathological signs of Th2/Th17 high experimental asthma in mice." (PMID 35883573, 2022). "Compared to men, TH17 cells of both women with severe asthma and healthy controls produced more IL-17A, increased the expression of IL-23R, while decreased let-7f microRNA expression." (PMID 36362795, 2022).
asthma (continued). "Altogether, IL-17A is a potential mediator to link Candida albicans sensitization and ED visits for asthma." (PMID 35740474, 2022). "In line with that, simultaneous induction of IL-13 and IL-17A led to pronounced airway hyperresponsiveness (AHR) in a mouse model of experimental asthma." (PMID 35883573, 2022). "It is consistent with the previous in vitro study demonstrating the enhancement of IL-17A production from T cells of steroid-resistant asthma patients by Dex." (PMID 35625602, 2022). "In asthma, to our best knowledge, our findings firstly provide evidence that IL-17A is a potential mediator to link Candida albicans sensitization and poorer clinical outcomes." (PMID 35740474, 2022). "The immune function of asthma children and healthy children was evaluated by detecting IgE concentration, eosinophil count, IL-4, and IL-17A." (PMID 35356750, 2022). "IL-17A is associated with AHR and neutrophilic inflammation, and some studies have reported that IFN-γ is detrimental in asthma pathogenesis." (PMID 36477357, 2022). "Elevated IL-17A expression was detected in the airway biopsy specimens and sputa from patients with moderate-to-severe asthma." (PMID 35625602, 2022). "Some of the researched monoclonal antibodies (e.g. anti-IL-13 tralokinumab and lebrikizumab or anti-IL-17A secukinumab) have shown optimistic results in preliminary research; however, these have been discontinued in asthma clinical research." (PMID 36561741, 2022). "Noteworthy, although IL-17F belongs to the Th17 lineage, and in sharp contrast with the deleterious asthma outcomes of IL-17A, it has a protective effect on experimental asthma development." (PMID 36233196, 2022). "Recently, a phase I trial studying the effect of a bispecific anti-IL-13 and anti-IL-17A antibody in asthma was early terminated due to high frequency of treatment immunization." (PMID 35386663, 2022). "The inhibition of IL-17A production in Th17 cells by an RV infection in the setting of asthmatic children and experimental mice asthma lends further credence to this notion." (PMID 36032162, 2022). "It was observed that, in this study, higher IgE concentration, eosinophil count, IL-4, and IL-17A levels were revealed in the asthma exacerbation children than in the remaining children; what is more, these levels increased with the severity of asthma." (PMID 35356750, 2022). "A Phase II RCT investigated the subcutaneously administered anti-IL-17A mAb CJM112 300 mg when added to existing therapy in patients with inadequately controlled moderate to severe asthma, with low serum IgE and BEC." (PMID 36140430, 2022). "Typically, severe steroid-unresponsive asthma characterized by neutrophilia exhibits a Th2-low and Th17-high airway inflammation, with elevated levels of IL-17A, IL-17A/F and TNF-α at mucosal surfaces of the airway." (PMID 36517803, 2022). "For example, IL-17A is a potential mediator to link Candida albicans sensitization and poor outcomes for asthma." (PMID 36078171, 2022). "Recently, the mingling of Th1 and Th17-associated cytokine expression patterns also manifest in asthma, as demonstrated by the presence of IFN-γ+ IL-17A+ Th cells in the lower airways of children with severe treatment-refractory asthma." (PMID 36032162, 2022). "In the viral-mediated exacerbation of OVA-induced mice asthma, up to three fourths of total lung-infiltrating γδ T cells are Th17-like γδT, constituting 20–40% of total IL-17A+ cells in that compartment." (PMID 33661375, 2021). "For instance, IL-17A contributes to asthma pathogenesis and exerts synergistic effects with IL-13 to induce airway hyper responsiveness." (PMID 33441700, 2021). "In human severe asthma patients high levels of IL-17A were found in induced sputum and bronchial biopsies." (PMID 33717165, 2021). "We also demonstrated that targeted deletion of IL-17A in T cells impaired OAS1 genes downstream of IFN-beta and RV inhibited IL-17A in CD4+ T cells in a setting of asthma." (PMID 34691038, 2021).